LTBP1 (latent transforming growth factor beta binding protein 1)
Description:
Key regulator of transforming growth factor beta (TGFB1, TGFB2 and TGFB3) that controls TGF-beta activation by maintaining it in a latent state during storage in extracellular space. Associates specifically via disulfide bonds with the Latency-associated peptide (LAP), which is the regulatory chain of TGF-beta, and regulates integrin-dependent activation of TGF-beta. Outcompeted by LRRC32/GARP for binding to LAP regulatory chain of TGF-beta.
Synonyms: ARCL2E
Tractability: Antibody: UniProt places it where antibodies can reach, with high confidence; its Gene Ontology location is reachable by antibodies, with high confidence; UniProt predicts a signal peptide or a membrane-spanning region. PROTAC: ubiquitination databases record sites on it.
Gene: Protein-coding gene on chromosome 2 (32,946,472 to 33,399,509, forward strand). Ensembl gene ENSG00000049323.
Subcellular location: Secreted; Secreted, extracellular space, extracellular matrix
Pathways (Reactome):
Metabolism of proteins: Post-translational protein phosphorylation; Regulation of Insulin-like Growth Factor (IGF) transport and uptake by Insulin-like Growth Factor Binding Proteins (IGFBPs)
Extracellular matrix organization: Molecules associated with elastic fibres
Signal Transduction: TGF-beta receptor signaling activates SMADs
Gene Ontology:
Molecular function: microfibril binding; molecular adaptor activity; protein binding; receptor ligand inhibitor activity; transforming growth factor beta binding; extracellular matrix structural constituent; protein sequestering activity; transforming growth factor beta receptor activity; calcium ion binding
Biological process: establishment of protein localization to extracellular region; transforming growth factor beta production; cell surface receptor protein serine/threonine kinase signaling pathway
Cellular component: extracellular matrix; extracellular region; microfibril; protein-containing complex; elastic fiber; endoplasmic reticulum lumen; non-collagenous component of interstitial matrix; transforming growth factor beta complex
Genetic constraint (gnomAD): Loss-of-function variants: 113 observed, 180.73 expected, observed/expected ratio (o/e) 0.63, 90% interval 0.54 to 0.73. The synonymous counts are far from expectation, so gnomAD's model fits this gene poorly and the ratio says little. Missense variants: 2,069 observed, 1,986.1 expected, observed/expected ratio (o/e) 1.04, 90% interval 1 to 1.08. Synonymous variants: 890 observed, 746.09 expected, observed/expected ratio (o/e) 1.19, 90% interval 1.13 to 1.26.
Homologues: Orthologues: chimpanzee LTBP1 (99% identical), macaque LTBP1 (99% identical), pig LTBP1 (93% identical), rabbit LTBP1 (92% identical), dog LTBP1 (92% identical), rat Ltbp1 (90% identical), guinea pig LTBP1 (86% identical), mouse Ltbp1 (74% identical), tropical clawed frog ltbp1 (62% identical), zebrafish ltbp1 (45% identical). Paralogues in human: LTBP2 (40% identical), LTBP4 (31% identical), LTBP3 (30% identical).
Diseases named in the same sentence as LTBP1 in open-access papers:
LTBP1 is named in the same sentence as 88 diseases in open-access papers, as found by Europe PMC text mining. Sharing a sentence is not in itself a finding about the gene and the disease. The quoted sentences say what the papers report.
breast carcinoma (6 papers, 2013 to 2023). "LTBP1 is associated with breast cancer progression and regulated by the WNT/Ca2+–CaMKII–NF-κB axis." (PMID 32216815, 2020). "ANGPTL4, PIEZO2, SCNN1A, LTBP1, and SerpinB2 promote the survival of breast cancer cells in the brain microenvironment." (PMID 37108248, 2023). "Higher mRNA expression was detected in FN1 and LTBP1 in breast cancers than normal population, with increasing expression levels from primary to metastatic cancers, whereas ATF3 had reversed expression patterns." (PMID 33500735, 2021). "Gain of LTBP gene expression also has pathological consequences: LTBP1 is upregulated in two breast cancer metastasis signatures and is one of only six genes found in common to both." (PMID 24262428, 2013). "In most studies, LTBP1 is increasingly being considered to be an oncogene, and expression of LTBP1 is closely related to the activity of the Wnt signaling pathway and lung and bone metastasis in breast cancer." (PMID 36629522, 2022). "Elevation of LTBP1 appears to play a role in enhancing metastatic behavior in breast cancer." (PMID 32216815, 2020). "Among these candidates, SERPINE1, LTBP1, and THBS1 are involved in TGF-beta receptor signaling, which was reported previously to be regulated by the BRCA gene and to induce “BRCAness” in breast cancer." (PMID 34064977, 2021). "Although TGFβ is well-known as a tumor suppressor and metastasis promoter, and LTBP1 is elevated in two distinct breast cancer metastasis signatures, LTBPs have not been studied in the normal mammary gland." (PMID 24262428, 2013).
esophageal squamous cell carcinoma (5 papers, 2020 to 2025). Esophageal squamous cell carcinoma (ESCC) is a type of esophageal carcinoma (EC) that can affect any part of the esophagus, but is usually located in the upper or middle third. "LTBP1 has been implicated in promoting esophageal squamous cell carcinoma via EMT." (PMID 40430098, 2025). "In cancer studies, LTBP1 is highly expressed in esophageal squamous cell carcinoma (ESCC) tissues, and its overexpression is positively correlated with lymph node metastasis." (PMID 41019096, 2025). "In esophageal squamous cell carcinoma, a positive correlation between FN1 and LTBP1 has been demonstrated." (PMID 37947594, 2023).
depression (4 papers, 2018 to 2025). "Some studies have also explored the potential bridging role of LTBP1 between depression and glioblastoma and found that LTBP1 affects glioblastoma and depression/anxiety disorders by regulating the organization and function of the ECM." (PMID 41019096, 2025). "And LTBP1 and its target TGF-β1 were also involved in Alzheimer disease and depression." (PMID 33059753, 2020).
glioblastoma (4 papers, 2020 to 2025). The most malignant astrocytic tumor (WHO grade IV). "Also, glioblastoma cells with high LTBP1 expression have a significantly greater proliferation and migration capacity, making it an important molecule that influences the prognosis of glioblastoma patients." (PMID 41019096, 2025).
glioma (4 papers, 2016 to 2021). A benign or malignant brain and spinal cord tumor that arises from glial cells (astrocytes, oligodendrocytes, ependymal cells). "In order to analyze the function of LTBP1 on the tumor biology of gliomas, function enrichment analysis was conducted using the top 150 up and down regulated DEGs." (PMID 33059753, 2020). "And the expression of LTBP1 in primary gliomas is significantly lower than recurrent gliomas, P<0.001." (PMID 33059753, 2020). "In detail, expression of LTBP1 in recurrent WHO IV glioma is significantly higher than primary WHO IV glioma, P<0.05." (PMID 33059753, 2020). "The Kaplan–Meier analysis that lower expression of LTBP1 have better prognosis than higher LTBP1 expression for both primary and recurrence gliomas." (PMID 33059753, 2020). "On the other side, it was also reported that LTBP1 was closely involved in the processes of glioma." (PMID 33059753, 2020). "FN1, COL1A1, COL6A1, and LTBP1 were significantly expressed in GBM compared with WHO grade II and III glioma." (PMID 34638384, 2021). "LTBP1 expression level were decreased by about 5-fold in CLL patients, but were reported to increase in human glioma cells." (PMID 27078856, 2016). "We firstly confirmed the negative influence of LTBP1 on the outcome of gliomas with the data from Chinese Glioma Genome Atlas." (PMID 33059753, 2020). "Intriguingly, LTBP1 increases TGF-β1 and TGF-β2 at the same time in glioma cells.Thus, LTBP1 could inhibit BMP signaling by activating the TGF-β signaling pathway." (PMID 27907131, 2016). "1p/19q codeletion gliomas had lower expression of LTBP1 than non-codeletion, P<0.0001." (PMID 33059753, 2020). "In detail, significantly different expression of LTBP1 between 1p/19q codeletion and non-codeletion was existed in WHO III and IV gliomas but not in WHO II gliomas, P<0.0001." (PMID 33059753, 2020). "No significant expression difference of LTBP1 existed between primary and recurrent WHO II and III gliomas." (PMID 33059753, 2020). "In detail, significantly different expression of LTBP1 between IDH-mutant and wildtype was existed in WHO IV but not II and III gliomas, P<0.0001." (PMID 33059753, 2020).
cervical cancer (3 papers, 2022 to 2024). A primary or metastatic malignant neoplasm involving the cervix. "LTBP1 was lowly expressed in cervical cancer, and the inhibition of LTBP1 can improve the malignant degree of the tumor, and this process can be blocked by carboplatin." (PMID 36629522, 2022). "Although in most of the current studies, LTBP1 increasingly appeared as an oncogene, in our study, we confirmed that LTBP1 had a low expression in cervical cancer tissue samples compared with that in adjacent tumor tissue." (PMID 36629522, 2022). "In conclusion, we confirmed the role of LTBP1 in cervical cancer and provided a reference for blocking the increase of tumor metastasis caused by LTBP1 deletion." (PMID 36629522, 2022). "In the clinical samples, expression of LTBP1 was found to be increased in tumor tissue obtained from patients with cervical cancer that were resistant to carboplatin." (PMID 36629522, 2022). "Through further cell biology experiments, we confirmed that the inhibition of LTBP1 can promote the proliferation and metastasis of tumor cells, further indicating that LTBP1 functions as a tumor suppressor gene in cervical cancer." (PMID 36629522, 2022). "Similar to HELA cells in vivo results, the GFP signal was highly enhanced in the LTBP1 shRNA group, suggesting that low expression of LTBP1 could increase the metastatic ability of cervical cancer cell lines." (PMID 36629522, 2022). "In our in-house samples, LTBP1 was lowly expressed in cervical cancer tissues." (PMID 36629522, 2022). "The overall survival rate of patients with cervical cancer and expression of LTBP1 was significantly lower, which preliminarily confirmed that in cervical cancer, LTBP1 might be a tumor suppressor gene." (PMID 36629522, 2022). "Similar to mRNA level, the LTBP1 protein level was low in cervical carcinoma tissues." (PMID 36629522, 2022). "However, the association between LTBP1 and cervical cancer has not been reported." (PMID 36629522, 2022). "We then investigated the expression of LTBP1 in cervical cancer cell lines and found that HELA and HT-3 had a relatively higher LTBP1 protein level compared with 2 other cell lines." (PMID 36629522, 2022). "LTBP1 regulates the secretion of TGF-β1, but the exact mechanism of LTBP1-induced immune suppression signaling in cervical cancer remains unknown." (PMID 36629522, 2022).
epilepsy (3 papers, 2020 to 2025). A brain disorder characterized by episodes of abnormally increased neuronal discharge resulting in transient episodes of sensory or motor neurological dysfunction, or psychic dysfunction. "In two siblings with intellectual disability, psychomotor retardation, blindness, epilepsy, movement disorder and cerebellar atrophy we identified rare homozygous variants in the genes LTBP1, EMILIN1, CACNB4, MINAR1, DHX38 and MYO15 by whole-exome sequencing." (PMID 32176688, 2020). "LTBP1’s role in TGF-β activation leading to enhanced TGF-β/Smad signaling and inflammation are well-documented in epilepsy models, where inhibiting LTBP1 expression has shown to have neuroprotective effects." (PMID 39990858, 2024).
lung adenocarcinoma (3 papers, 2021 to 2024). A carcinoma that arises from the lung and is characterized by the presence of malignant glandular epithelial cells. "LTBP1 promotes the proliferation of lung adenocarcinoma cells, while its high expression in hepatocellular carcinoma inhibits cancer progression." (PMID 36620585, 2022). "Together, we identified a rare triple ALK fusion variant, ALK-LRRN2, LTBP1-ALK and HIP1-ALK, in a patient with lung adenocarcinoma." (PMID 34941039, 2021). "Latent TGF-β Binding Protein 1 (LTBP1) was identified as a CD109-interacting protein in lung adenocarcinoma and their interaction is crucial for tumor invasion and inflammation in lung adenocarcinoma." (PMID 39990858, 2024).
malignant glioma (3 papers, 2014 to 2021). A grade III or grade IV glioma arising from the central nervous system. "In contrast, some other studies suggest that constitutive AhR activity positively controls TGFβ1, TGFβ2, and LTBP-1 in malignant glioma cells." (PMID 24795504, 2014). "In another study, silencing of LTBP1 expression increases cell proliferation in malignant glioma." (PMID 32216815, 2020). "Silence of LTBP1 reduces TGF-β activity and Smad2 phosphorylation without affecting TGF-β protein levels in malignant glioma cells." (PMID 32216815, 2020).
pulmonary fibrosis (3 papers, 2020 to 2023). Chronic progressive interstitial lung disorder characterized by the replacement of the lung tissue by connective tissue, leading to progressive dyspnea, respiratory failure, or right heart failure. "In addition, ER stress can promote the protein expression of LTBP1 and LTBP4, which are closely related to the secretion of TGF-β1 and TGF-β4 in pulmonary epithelial cells, thereby playing a key role in the development of pulmonary fibrosis." (PMID 33097029, 2020).
anxiety disorder (2 papers, 2020 to 2025). A category of psychiatric disorders which are characterized by anxious feelings or fear often accompanied by physical symptoms associated with anxiety. "By a series of bioinformatic methods, we found that LTBP1 could be a bridge which link depressive/anxiety disorder and GBM." (PMID 33059753, 2020). "Bioinformatic mining revealed that LTBP1 could be a potential genetic mechanism in both depressive/anxiety disorder and GBM." (PMID 33059753, 2020). "And the potential mechanism of LTBP1 on both depressive/anxiety disorder and GBM could be result from the regulation of ECM in the brain." (PMID 33059753, 2020). "The changing of ECM by LTBP1 could function as an indicator of depressive/anxiety disorder and GBM by regulating inflammatory responses." (PMID 33059753, 2020). "Differentially expressed LTBP1 could change the components of ECM and stabilization of network, alter the neural plasticity and change the adhesion and interaction among of brain, which may result in susceptibility of neurological and psychological disorders, including depressive/anxiety disorders." (PMID 33059753, 2020). "However, there is neither evidence that can provide the exact mechanism of LTBP1 on depressive/anxiety disorder as well as GBM, nor any research focusing on the connection linking depressive/anxiety disorders and the prognosis of GBM." (PMID 33059753, 2020).
cardiomyopathy (2 papers, 2023). A disease of the heart muscle or myocardium proper. "Upregulated DEGs were associated with pro-fibrotic signaling, such as TGF-β signaling-associated genes (TGFB1, LTBP1, ANKRD1) and other cardiomyopathy-related signaling, such as the MAPK cascade (ADRA1A, EGR1, IL6R)." (PMID 37084237, 2023).
diabetes (2 papers, 2012 to 2013). "The remaining non-calcium ion channel genes in the sternohyoid, Slc16a3, Amy1a, Chrnd and Ltbp1 did not have changed expression in previous studies of diabetes." (PMID 24199937, 2013).
glaucoma (2 papers, 2012 to 2025). Increased pressure in the eyeball due to obstruction of the outflow of aqueous humor. "In the context of glaucoma, LTBP3 contributes to extracellular matrix remodeling, while mutations in LTBP1 have been identified in clinical families with AD." (PMID 40988281, 2025).
Hypertension (2 papers, 2013 to 2016). The presence of chronic increased pressure in the systemic arterial system. "Thus LTBP1 is responsible for the activation of MAPKs, and repressed LTBP1 may be a primary factor in the effect of L3MBTL4 on vascular remodeling and hypertension." (PMID 27480026, 2016).
liver fibrosis (2 papers, 2020 to 2025). "In addition, our MASH EVs were significantly enriched with several ligands that are crucial in mediating liver fibrosis, including PDGFB, LTBP1 and TIMP3." (PMID 40313415, 2025).
myocardial infarction (2 papers, 2020 to 2022). Gross necrosis of the myocardium, as a result of interruption of the blood supply to the area, as in coronary thrombosis. "The dramatic downregulation of THSD4, LEFTY2, and LTBP1 induced by melphalan treatment could collectively enhance the activation of TGF-β signaling pathway and impact the downstream cellular processes such as the induction of apoptosis as observed in myocardial infarction." (PMID 33153480, 2020).
osteoarthritis (2 papers, 2016 to 2022). A noninflammatory degenerative joint disease occurring chiefly in older persons, characterized by degeneration of the articular cartilage, hypertrophy of bone at the margins and changes in the synovial membrane. "We found evidence (MR p < 0.05) for a causal effect of methylation on gene expression levels for two genes (ALDH1A2 and RPP25) in low-grade osteoarthritis cartilage and one gene (LTBP1) in high-grade osteoarthritis cartilage." (PMID 35679866, 2022). "For seven genes (ALDH1A2, CHMP1A, CRADD, FAM53A, LTBP1, RPP25, and TGFA), we found evidence that GWAS signals for osteoarthritis colocalize with mQTLs in these genes and are additionally associated with gene expression levels in the same tissue." (PMID 35679866, 2022). "We found such an eQTL effect below nominal significance levels for five genes in low-grade osteoarthritis cartilage (ALDH1A2, CHMP1A, FAM53A, RPP25, and TGFA), two genes in high-grade osteoarthritis cartilage (FAM53A and LTBP1), and one gene in synovium (CRADD)." (PMID 35679866, 2022).
osteoporosis (2 papers, 2018 to 2019). A condition of reduced bone mass, with decreased cortical thickness and a decrease in the number and size of the trabeculae of cancellous bone (but normal chemical composition), resulting in increased fracture incidence. "The genes identified in our study—LTBP1, PZP, ARID2, and HEBP1 in osteoporosis BRON patients—clearly support the previous evidence that angiogenesis, osteoclast activity, bone remodeling, and immune responses are critical underlying mechanisms." (PMID 31747953, 2019). "Among the affected proteins involved in the TGF‐β pathways, TGF‐β1, LTBP1, and STAT were downregulated in the SDEs of patients with osteoporosis." (PMID 29603567, 2018). "Excluding genes without known specific functions (CDC27 and TNRC18), ARID2, HEBP1, LTBP1, and PLVAP were the only significant differences in the cancer group revealed by the gene-score methodology, while DFFA, FAM193A, and VEGFA were the only significant differences in the osteoporosis group." (PMID 31747953, 2019).
thoracic aortic aneurysm (2 papers, 2016 to 2022). An aneurysm formed in the wall of the proximal portion of the descending aorta proceeding from the arch of the aorta. "Anomalous expression of LTBP1 has been previously detected in thoracic aortic aneurysms and may promote the development of arterial diseases." (PMID 35886043, 2022).
alcohol dependence (1 paper, 2012). Physical and psychological dependence on alcohol. "The two relevant genes, LTBP1 and FGD4, may play important roles in the metabolism of alcohol dependence." (PMID 22295116, 2012).
aneurysm (1 paper, 2022). Bulging or ballooning in an area of an artery secondary to arterial wall weakening. "Despite this possibility, a more-recent study described eight individuals aged between 1.5 and 17 years carrying bi-allelic truncating variants in LTBP1 and none was reported to suffer from aneurysm." (PMID 35098309, 2022).
aneurysmal disease (1 paper, 2022). "In summary, although mutations in LTBP3 have been linked to human aneurysmal disease, the causality of deletions involving the LTBP1 locus remains speculative." (PMID 35098309, 2022).